INS (insulin)
Diseases named in the same sentence as INS in open-access papers (continued):
Sharing a sentence is not in itself a finding about the gene and the disease.
Anxiety (continued). "Notably, IG administration of furimazine has similar effects of controlling blood glucose homeostasis as IP or IV administration, which is a critical favorability criterion because it avoids the pain and anxiety caused by the traditional intramuscular injection of insulin." (PMID 33504786, 2021). "At 95% CI, our analysis reveals that female ADEN present with osteoporosis, unspecified cancer, anxiety, and urinary tract infections and are placed on insulin use." (PMID 40491970, 2025). "We found that IF rapidly decreased the BMI, insulinconcentration, insulin sensitivity, and anxiety symptoms and reduced FC betweenthe laterobasal amygdala and PG." (PMID 40630882, 2025). "In contrast, our analysis revealed that at 95% CI, female patients are likely to present with osteoporosis, unspecified cancer, anxiety, and urinary tract infections and are placed on insulin use." (PMID 40491970, 2025). "Future studies should explore the role of amygdala-specific insulin signaling in both stress responses and anxiety." (PMID 40978196, 2025). "In the infographic, older adults were keen to include how having access to their insulin reduced their anxiety." (PMID 41358572, 2025). "Although differences were not statistically significant, this pattern aligns with evidence connecting insulin resistance to depressive and anxiety symptomatology." (PMID 41464315, 2025). "Mothers often navigate uncertainty and anxiety while balancing strict insulin schedules and dietary plans with domestic responsibilities and financial constraints." (PMID 40938912, 2025). "Regarding psychological experiences, some patients experienced anticipatory anxiety about potential pain during insulin injections or blood glucose monitoring." (PMID 41358642, 2025). "Intranasal delivery of insulin in awake mice can facilitate the passage of regulatory and metabolic hormones across the blood–brain barrier, resulting in improved mood and reduced anxiety in rats." (PMID 40429455, 2025). "Future research should explore the role of insulin delivery methods to better understand their influence on anxiety patterns, self-monitoring practices, and performance outcomes in elite athletes with T1D." (PMID 39823464, 2025). "The psychological burden of T1DM extends to children and adolescents, who frequently experience anxiety, self-blame, and social isolation due to their dietary restrictions and dependence on insulin." (PMID 40938912, 2025). "In the healthy obese group, a different network was identified, incorporating stress and anxiety variables that influenced blood pressure, anthropometry, and insulin levels." (PMID 39275240, 2024). "Preoperative carbohydrate drinks have been shown to significantly improve patient comfort, especially in terms of hunger, thirst, fatigue, anxiety and nausea, by reducing postoperative insulin resistance." (PMID 39095723, 2024). "All T1D patients, regardless of transplantation status, experienced stress (33.4%), anxiety (27.9%), decreased physical activity (42.0%), weight gain (40.5%), and increased insulin requirements (29.7%)." (PMID 38601276, 2024). "The emergence of evidence has revealed that the modulation of dopamine release via the astrocyte insulin signaling pathway, which is achieved by the regulation of ATP release, ultimately exerts depressive-anxiety-like behavioral patterns." (PMID 38916735, 2024). "In clinical trials, NADH supplementation in patients with Parkinson’s disease and chronic fatigue syndrome led to improvements in heart rate, reductions in anxiety, and enhanced insulin signaling." (PMID 39728553, 2024). "For instance, swimming exercise in T2DM C57BL/6 mice notably decreased insulin resistance and brain oxidative stress, thereby alleviating anxiety-like behaviors." (PMID 40226688, 2024). "Glu, typically elevated in anxiety, impacts insulin secretion through Ca2+ signaling and can lead to β-cell death by activating N-methyl-D-aspartate receptors." (PMID 40226688, 2024).
Anxiety (continued). "We also consider the actions of insulin on SPNs and on striatal astrocytes, as well as the broader implications of the actions of insulin in the striatum on dopamine release regulation and its possible role in anxiety and depressive-like behaviors." (PMID 36979453, 2023). "Following up on these results, we then show that activation of Akt1, a central hub in the insulin pathway, alleviates long‐term memory decline and ameliorates altered anxiety levels in the APP/PS1 transgenic AD mouse model." (PMID 37984409, 2023). "In this study, we report the first examination of body composition, peripheral insulin sensitivity, and glucose tolerance in relation to behavioral assessments of learning, memory, and anxiety in the TgF344‐AD rat model of AD." (PMID 37095621, 2023). "In conclusion, we report the first assessment of body composition, peripheral glucose tolerance, and peripheral insulin sensitivity in the TgF34‐AD rat model in conjunction with a behavioral battery to assess cognition and anxiety." (PMID 37095621, 2023). "In this pilot study GDM was associated with differences in psychological wellbeing, specifically increased anxiety in women treated with insulin." (PMID 36733299, 2023). "HbA1c was unchanged, likely because anxiety about hypoglycaemia proved a barrier to adequate insulin dose titration." (PMID 37562398, 2023). "Studies suggest that frequent intake of dietary fiber mitigates anxiety, slows the absorption of carbohydrates, and enhances insulin sensitivity, thus better controlling blood glucose." (PMID 37764713, 2023). "Some benefits of physical activity can be achieved immediately, such as reduced feelings of anxiety, reduced blood pressure, and improvements in sleep, some aspects of cognitive function, and insulin sensitivity." (PMID 37836485, 2023). "Disappointment, shame, anxiety, frustration, despondency and self‐blame were attributed to insulin initiation, perceived as indicating failure to take care of self." (PMID 35441727, 2022). "Voluntary exercise strengthened general activity rhythms, improved memory and lowered anxiety- and depressive-like behaviors, enhanced oral glucose tolerance, and decreased plasma insulin levels and liver weight." (PMID 35165331, 2022). "Lifelong illness, the need for insulin injections, and life-threatening and debilitating complications can greatly increase maternal anxiety." (PMID 35562744, 2022). "This conclusion is supported by the regression analyses that show both binge eating and T-scored RCADS separation anxiety are predicted by a combination of being maintained by insulin pump injection, self-esteem, coping behaviour, and sleep-related problems." (PMID 36508408, 2022). "Daily rhythms of general locomotor activity and blood glucose are strengthened, blood glucose and plasma insulin levels are lowered, oral glucose tolerance is enhanced, and tests of depressive- and anxiety-like behaviors and memory are improved." (PMID 35165331, 2022). "Previous studies indicated that higher levels of plasmatic glucose alter insulin and IGF1 receptors activities in different brain regions, such as the hippocampus, boosting the onset of anxiety and memory loss." (PMID 36405951, 2022). "One narrative review specifically addressed insulin adherence in adolescents with T1D, considered mainly psychological factors (e.g., mood, anxiety, and eating disorders), social support factors, and interactions with healthcare system factors." (PMID 35673417, 2022). "He expressed his anxiety about his new insulin regimen since he believed that the previous doses were higher and worked better than the ones prescribed at the hospital by the endocrinologist." (PMID 34873761, 2022). "Elevations in the levels of IR, IRS2, and neurogenesis markers after insulin administration support a decrease in anxiety-like behaviors and an increase in learning and memory in rats." (PMID 36474571, 2022).
Anxiety (continued). "In this study, we aimed to examine the level of hippocampal neurogenesis, and assess learning and anxiety and the level of some proteins involving insulin signaling pathways in rats with MetS, and to reveal the relationship among them." (PMID 36474571, 2022). "Several factors, such as stigmatisation, and daily insulin injections, were partly responsible for the adverse reports of stress and anxiety." (PMID 36425875, 2022). "One of the possibilities for the mechanism of action is the insulin modulation of brain serotonergic neurons and their neurotransmission, resulting in the development of anxiety and depressive symptoms." (PMID 36232867, 2022). "The sand rats that showed diminished BDNF circadian rhythms also demonstrated higher blood glucose and insulin levels, as well as significantly higher anxiety- and depressive-like behaviors compared to animals acclimated to neutral photoperiod." (PMID 35165331, 2022). "Several measures were obtained during both conditions (plasma, insulin, glucagon, cortisol levels, testosterone and luteinizing hormone levels; skin conductance, heart rate and anxiety and desire to drink)." (PMID 36235578, 2022). "Although some studies showed IN insulin decreases anxiety-like behavior and improves various memory tasks, other studies were neutral, again pointing to the impact of dose, duration, genetic background, age of the animals, and insulin formation." (PMID 35058808, 2021). "In total, 48% of all participants who were on non-insulin treatment and 91% of Belgians, for whom T2DM had lasted ∼1.6 years, expressed anxiety about insulin use." (PMID 34338125, 2021). "They found it was significantly worse during lockdown and the use of insulin therapy was significantly higher, which the authors ascribe to the reduced physical activity, changed dietary habits and higher levels of anxiety during lockdown." (PMID 33810256, 2021). "Overall, our findings show that high-dose RIB induced depressive- and anxiety-like behavior and spatial memory impairment in mice, and highlight the involvement of the insulin-POMC-MEK-TCF7L2 pathway in the hippocampus." (PMID 33531473, 2021). "We here expand our earlier work that showed a role for the MAPK‐specific Dusp8 as gatekeeper for insulin resistance, cognition, and anxiety behavior in mice." (PMID 33131190, 2021). "At present, the main clinical treatment is insulin injection, while insulin dose, pain of injection, anxiety, and social acceptability bringing great physical and mental trauma to the patients." (PMID 34095316, 2021). "Compared with the control group, the PCOS group showed higher luteinizing hormone (LH) and serum insulin levels, worse sleep quality, increased depressive and anxiety state scores, and memory and executive function impairments." (PMID 33362718, 2020). "The previous findings clearly differed from those observed in our patient, who did not experience hypokalemia but showed stiffness of truncal muscles (while extremities were spared) upon insulin injections, sound, stress, or anxiety." (PMID 32982980, 2020). "After 8 weeks of insulin administration via the nasal cavity, memory was improved and anxiety symptoms were alleviated." (PMID 32281722, 2020). "Other reasons reported included preventing self-trauma due to anxiety, to facilitate administration of ophthalmic medications, and, in one case, to protect an owner from being bitten when they administered insulin injections to a diabetic, “needle-phobic” dog." (PMID 32093257, 2020). "Initially, in the early period, when it is first diagnosed, the young patients usually express sadness, anxiety, irritability, despondency, and negativism in taking insulin or attending school." (PMID 33374577, 2020). "Despite these issues, individuals with certain stress levels and anxiety do experience a decrease in insulin release; therefore, it reduces the disposal of glucose." (PMID 31485387, 2019).
Anxiety (continued). "Many factors influence an individual's glycemic response to exercise including the type, intensity and duration of the activity, the amount of insulin on board and the person's stress/anxiety levels." (PMID 31258513, 2019). "Reducing the time of fasting preoperatively is meant to decrease the feeling of anxiety, hunger, and starvation-induced insulin resistance." (PMID 30508899, 2018). "Butyrate concentrations inversely correlated with anxiety levels, whereas propionate directly correlated with insulin levels and with the relative abundance of Roseburia inulinivorans, a known propionate producer." (PMID 28636668, 2017). "Trait anxiety score, insulin data and HOMA-IR were unavailable for two women (both from the higher fit group)." (PMID 28081200, 2017). "One of the prime reasons for rejecting the insulin therapy is related to psychology (e.g., anxiety) of patients." (PMID 29333459, 2017). "Other anxiety‐related tests such as light–dark test and elevated plus maze are needed to validate the anxiety level of these mice and the anxiolytic effect of intranasal insulin in these mice." (PMID 27457264, 2016). "APP/PS1 mice also exhibited increased anxiety level, as assessed by open‐field test in our study, which was alleviated by intranasal insulin treatment." (PMID 27457264, 2016). "Education motivates patients to respond to the challenges of insulin therapy, eliminates stress and prevents anxiety about the future." (PMID 27955676, 2016). "In this pragmatic explorative study, we found that successful diet-induced weight loss can be predicted in overweight adults with T2D by the baseline variables fasting glucose, anxiety, numb feeling in extremities, insulin dose and waist-to-hip ratio." (PMID 27494531, 2016). "We chronically administered the stress hormone corticosterone (CORT), which induces anxiety/depressive-like behavior and normally increases plasma insulin levels, via the drinking water for 10 weeks, and we examined the stress response in KO mice." (PMID 25754523, 2015). "Preoperative carbohydrate drinks significantly improved insulin resistance and indices of patient comfort following surgery, especially hunger, thirst, malaise, anxiety and nausea." (PMID 24417824, 2014). "There are a number of possible mediators of the effect of diet on anxiety-like behaviour, including both peripheral and central mediators such as corticosteroids, insulin leptin, acetylcholine, serotonin, opioids and dopamine." (PMID 24027581, 2013). "Two UK studies found that compared with oral hypoglycaemic drug treatment alone, insulin injection treatment significantly improved patients’ subjective well-being, in particular, at the expense of a higher degree of anxiety." (PMID 23964785, 2013). "At baseline, 59.2% of exenatide BID and 53.8% of insulin patients had responses “within the normal range” for anxiety." (PMID 24369764, 2013). "Insulin emerged as a predictor in only two of the fourteen statements, focused on anxiety (OR = 0.14, 95% CI: 0.05–0.41, P = 0.00) and disbelief of insulin therapy (OR = 0.20, 95% CI: 0.06–0.63, P = 0.01)." (PMID 23251799, 2012). "Our results suggest that pyridoxine treated in combination with insulin and A. marmelose has a role in the regulation of insulin synthesis and release, normalising diabetic related stress and anxiety through hippocampal serotonergic function." (PMID 20868513, 2010). "Patients on insulin therapy commonly face problems such as needle anxiety, fear of injection pain, and inconvenience of administration, troublesome dosing schedule, and social stigma." (PMID 17683531, 2007). "Together, this may suggest that differences in amygdala insulin signaling, whether pre-existing or altered by stress exposure, correspond with differential resilience and vulnerability to anxiety-like behavior after stress." (PMID 40978196, 2025). "Furthermore, insulin is known to enhance learning and memory and influence neurobehavioral conditions such as anxiety and depression." (PMID 40436945, 2025).
Anxiety (continued). "In addition, insulin also reduces anxiety-related behaviors and improves performance in the reversal MWM test in APP/PS1 mice." (PMID 41146261, 2025). "The lack of association to treatment could be due to the free access to technology in Denmark, where anyone with anxiety of needles or FoH would be offered insulin pump and sensor." (PMID 41212850, 2025). "Furthermore, anxiety symptoms can increase the release of stress hormones, such as cortisol, which can promote abdominal fat gain and insulin resistance." (PMID 38751589, 2024). "A study discovered that a high-fat diet (HFD) not only induces anxiety and anhedonia but also disrupts intracellular cascades related to synaptic plasticity, insulin signaling/glucose homeostasis (including Akt, extracellular signal-regulated kinase (ERK), and P70 S6 K)." (PMID 38680928, 2024). "The primary objective of this study was to determine postoperative blood glucose levels, with secondary objectives including the incidence of POH, postoperative insulin levels, blood urea levels, patient comfort, and the quality of perioperative care in terms of hunger, thirst, and anxiety." (PMID 38700117, 2024). "The obtained results indicate that insulin and IR are significantly associated with a particular depressive clinical presentation, anhedonia, state and trait anxiety and impaired sleep as well as non-response to SNRI." (PMID 38980569, 2024). "On the other hand, hyperkinesis in dark phase and anxiety, clearly reported for both models, could be connected with deregulated various clock‐controlled metabolic genes involved in insulin signaling and mitochondrial function, for example, Igf1r and Slc2a1." (PMID 39604147, 2024). "Our study showed that women with GDM who required treatment with insulin were at higher risk of poor psychological health during pregnancy, specifically anxiety, compared with pregnant women who did not have GDM." (PMID 36733299, 2023). "Our study showed that women with GDM requiring treatment with insulin are at higher risk of anxiety and their psychological wellbeing did not improve during the course of pregnancy." (PMID 36733299, 2023). "Furthermore, the MWM task and open field test showed that administration of WJMSC-CM and insulin significantly increased learning and memory capacity and attenuated anxiety-like behaviors." (PMID 37081849, 2023). "Our finding that more than 40% of women requiring insulin therapy were successfully treated with the SII regimen alone may help reduce this anxiety." (PMID 37283948, 2023). "Previous research has highlighted the need for insulin increased the perception of severity of the condition for women, and women described the progression to insulin as a constant threat, resulting in anxiety and fear returning, comparable to when first diagnosed." (PMID 37478148, 2023). "This might suggest that SAP treatment may itself have resulted in improved T1D management (as compared to multiple daily insulin injections) and supported sleep via a reduction in anxiety for example." (PMID 40303271, 2023). "Here, we found that growth hormone-releasing hormone knockout (GHRH-KO) mice, a GH-deficiency mouse model characterized by extended lifespan and enhanced insulin sensitivity, showed a lower anxiety symptom and impairment of short-term object recognition memory and autism-like behaviors." (PMID 36672612, 2022). "Traditional syringe/vial insulin administration is accompanied by patient and clinician hurdles, including psychological insulin resistance, patients' anxiety about the consequences and harmful effects of insulin, and necessary dietary modifications or restrictions." (PMID 36381916, 2022). "More and more importance is attached to the relationship between anxiety plots and other alterations, including changed γ-aminobutyric acid levels, increased insulin secretion and insulin resistance, and oxidative stress, which provides a promising target for anxiolytics." (PMID 35855329, 2022).